IL10 (interleukin 10)
Diseases named in the same sentence as IL10 in open-access papers (continued):
Sharing a sentence is not in itself a finding about the gene and the disease.
Sepsis (continued). "Serum levels of MMP-9, MMP-10, TIMP-1, tumor necrosis factor (TNF)-alpha, and interleukin (IL)-10 were measured in patients with severe sepsis at the time of diagnosis and in healthy controls." (PMID 19799791, 2009). "The later phase of sepsis, characterized by the generation of immunosuppressive cytokines such as IL-10 and IL-4 is often referred to as compensatory anti-inflammatory response syndrome." (PMID 19442306, 2009). "In summary, we found that CB2 receptor activation by endogenously released cannabinoids contributes to mortality, bacterial invasion, IL-10 production, and immune cell death in sepsis." (PMID 19641602, 2009). "TH2 cytokines, central among them IL-10, are thought to contribute to immunosuppression and the development of sepsis." (PMID 20027315, 2009). "Logistic regression revealed that among the seven candidate risk factors (admission plasma gelsolin, IL-6, IL-10, TNF-α, albumin, age and sex), admission plasma gelsolin was the only independent factor able to predict the occurrence of severe sepsis." (PMID 18706105, 2008). "In murine models of sepsis, compartmental delivery of IL-10 has been shown to be beneficial, whereas systemic delivery showed no protection from lethality." (PMID 17472748, 2007). "Since its discovery over a decade ago, many studies have investigated the potential use of IL-10 to treat inflammatory diseases ranging from arthritis to sepsis." (PMID 17472748, 2007). "PN also resulted in significantly lower IGFBP-I levels compared with EN in septic animals, despite the greater recovery of IL-6 and IL-10 in PN-fed animals with sepsis." (PMID 17634149, 2007). "• The route of administration of nutrition (parenteral versus enteral) in sepsis influences circulating levels of IL-6 and IL-10 in rodents." (PMID 17634149, 2007). "The purpose of this study was to determine if there is a relationship between the IL-10 -1082 G/A, IL-6 -174 G/C and CD14 -260 C/T SNPs and risk for or outcome from sepsis in mechanically ventilated very low birth weight (VLBW) infants." (PMID 16611358, 2006). "Production of IL-10 can have a potentially beneficial effect by dampening excess inflammatory mediator production in sepsis." (PMID 16611358, 2006). "Increased levels of IL-10 have been shown to correlate with the development of sepsis or adverse outcome during sepsis." (PMID 16759367, 2006). "A number of experimental studies have shown implication of Th-2 cytokines, like IL-10, in immunosuppression after thermal injury as well as in sepsis." (PMID 16168063, 2005). "Even though there was a trend toward statistical significance regarding the association of the IL10-1082G/A gene polymorphism with the odds of EOS in the allelic model, future studies should confirm the impact of individual alleles on early-onset sepsis in premature neonates." (PMID 41598258, 2026). "At the same time, the AA genotype of the IL10-1082G/A polymorphism is a risk factor for elevated IL10 production and the development of sepsis due to Gram-negative bacteria, especially in Afro-Colombian patients." (PMID 41598258, 2026). "There are some studies which investigated one polymorphism in the IL10 gene, a guanine substitution with adenine in nucleotide 1082 of the gene (IL10-1082G/A) as a factor influencing IL10 levels and a potential candidate for the development of sepsis, both in adults and newborns." (PMID 41598258, 2026). "IL‐10 helps prevent hyperactivation of the innate immune system by inhibiting the effects of cytokines such as TNF‐α, IL‐1β, and IL‐6, thereby reducing the risk of multiple organ failure, and mitigating complications related to sepsis." (PMID 41573125, 2026). "This ratio not only reflects the intensity of the anti-inflammatory response (IL-10), but also quantifies the depletion of immune cells (lymphocyte), which is highly compatible with the “high-inflammatory-high-immunosuppressive” feature of sepsis." (PMID 41001389, 2025).
Sepsis (continued). "IL-10 plays a substantial role in the cytokine storm during sepsis." (PMID 40429966, 2025). "Calprotectin has been reported as a pivotal mediator during the immunosuppressive stage of late sepsis, an effect that may also be mediated by IL-10." (PMID 41301767, 2025). "There were less IL-10 producing CD4+ T cells in sepsis patients and the ones that were present were less able to respond to ex vivo stimulation than their healthy counterparts, which is somewhat congruent with other sepsis observations of a regulatory T cell compartment failure." (PMID 39935482, 2025). "Similarly, the anti-inflammatory cytokines IL-4 and IL-10 present in sEVs increase during the late stage of sepsis." (PMID 41010852, 2025). "This is an important area of future study as a failure of T cell IL-10 production may contribute to the immune dysregulation observed in sepsis." (PMID 39935482, 2025). "Having a higher TNF-α to IL-10 ratio is beneficial in sepsis survivors with weakened immune systems, as an earlier clinical study showed that a sustained overproduction of IL-10 is a predictor of sepsis severity and worsened outcomes." (PMID 41124072, 2025). "The possible role of immunosuppressive factors such as IL-10 in sepsis requires more research." (PMID 40185975, 2025). "Interestingly, we describe here that the regulatory function of sepsis-induced PCs is dual in that it involves both secretion of a suppressive cytokine (IL-10) and expression of a member of the checkpoint inhibitory ligands family (PD-L1)." (PMID 40155394, 2025). "Therefore, this study aimed to investigate the effects of cetirizine and dexamethasone (alone and in combination) on serum levels of MaR-1, TNF-α, IFN-γ, IL-1, IL-2, IL-6, IL-8, and IL-10 in a rat model of sepsis induced by CLP method." (PMID 41517447, 2025). "Thus, besides autoimmune diseases, the current results expand the immunoregulatory role of CD138+CD44+HLA-DRhigh PCs as IL-10 producers and regulators of T-cell proliferation after sepsis as well." (PMID 40155394, 2025). "Importantly, the depletion of Hotairm1, which facilitatesS100A9 nuclear accumulation, significantly reduced IL-10 andTGF-β production, further reinforcing the therapeutic potential of targetingS100A9 to mitigate sepsis-induced immunosuppression." (PMID 40458301, 2025). "This study aimed to investigate the effects of cetirizine and dexamethasone (alone and in combination) on serum levels of Maresin-1 (MaR-1), TNF-α, IFN-γ, IL-1, IL-2, IL-6, IL-8, and IL-10 in a rat model of sepsis induced by the cecal ligation and puncture (CLP) method." (PMID 41517447, 2025). "In CLP-induced sepsis models, IL-10 levels were found to increase." (PMID 41517447, 2025). "Indeed, previous studies have attributed the survival advantage of females in sepsis to increased levels of interleukin-10 (IL-10), an anti-inflammatory mediator." (PMID 40890875, 2025). "IL-10 exerts multiple immunosuppressiveeffects during sepsis." (PMID 40458301, 2025). "In a porcine model, IL-10 levels peaked at the 16th hour of sepsis." (PMID 41517447, 2025). "IL-10 has been found to play a crucial role in reducing excessive inflammation during sepsis." (PMID 40885907, 2025). "The results demonstrate that IL-18, IL-6, MCP-1, and IL-10 are increased in sepsis, while IL-18 may serve as an additional biomarker for distinguishing abdominal from non-abdominal sepsis." (PMID 40510342, 2025). "The immunosuppressive state of sepsis is characterized by an overproduction of anti-inflammatory cytokines (e.g., IL-10) and a significant decrease in the number of lymphocytes, which together constitute the core features of immune dysfunction in septic patients." (PMID 41001389, 2025). "We next tested whether IL-10 production is required for maintenance of triglyceride levels during sepsis." (PMID 39951524, 2025). "Indeed, overproduction of circulating levels of IL-6, TNFα, and IL-10 were accompanied by the development of hypothermia during different animal models of sepsis." (PMID 40534875, 2025).
Sepsis (continued). "In the later phases of sepsis, sCD163 has been shown to lead to the release of IL-10." (PMID 40429966, 2025). "Importantly, we identify the persistence of biomarkers such as S100A8/A9, IL-10, mtDNA, and histone lactylation as molecular signatures of a Post-Sepsis Cellular Remnant." (PMID 41007702, 2025). "Thus, the trend for an increase in IL-10 in the CLP mice followed this concept, and the IL-10 levels were further increased in mice receiving hTSCs after the onset of CLP-induced sepsis." (PMID 40691621, 2025). "However, high levels can lead to immune suppression in sepsis survivors by promoting Treg expansion through IL-10 production, leading to chronic immune dysfunction." (PMID 40076848, 2025). "Instead, fluoxetine increases circulating levels of interleukin-10 (IL-10), which in turn protects from sepsis induced hypertriglyceridemia, preventing cardiac effects including impairment of glucose oxidation, ectopic lipid accumulation, ventricular stretch, and possibly cardiac failure." (PMID 39951524, 2025). "Notably, invivo depletion of long noncoding Ribonucleic Acid (RNA)Hotairm1, which induces S100A9 proteinaccumulation in MDSCs during late sepsis, reduced IL-10 and TGF-βproduction ex vivo." (PMID 40458301, 2025). "High IL-10 correlates with immunosuppression and poor outcome in late sepsis." (PMID 41268545, 2025). "However, both cytokines are frequently elevated in patients with sepsis, suggesting that the increase in IL-10 represents a compensatory response that is insufficient to prevent disease progression." (PMID 41158471, 2025). "Several possibilities for sepsis-induced monocyte/macrophage exhaustion include increased production of the anti-inflammatory cytokine IL-10, down-regulation of the NF-κB signaling pathway, decreased HLA-DR expression, and reduced lymphocyte signaling due to lymphocyte cell death." (PMID 38255280, 2024). "To determine whether IL-10 regulates DEL-1 expression in the bone marrow during sepsis, we treated neonate septic mice with an IL-10 receptor-blocking antibody (anti-IL-10R)." (PMID 38263289, 2024). "We compared the effects of two treatments, antibiotics and FMT, on the levels of inflammatory factors, including the proinflammatory factors TNF-ɑ, IFN-γ, IL-1b, and IL-6, and the anti-inflammatory factor IL-10, in the serum and alveolar lavage fluid of pneumonia-induced sepsis model mice." (PMID 38903943, 2024). "Levels of serum IL-6, TNF-α, and IL-10 in sepsis mice treated with anti-PD-L1 antibody significantly declined at 24 (P = 0.004), 48 (P = 0.006), and 72 h (P = 0.005), respectively; there were no significant changes at other time points, showing no statistical significance." (PMID 37776443, 2024). "Moreover, IL-10, which is considered predictive of fatal outcome in sepsis, was also more abundant in WT compared to that of KO at 24 hours post-CLP." (PMID 38720893, 2024). "IL-10 production by NK cells could prevent immunopathology, as was found in mouse models for cerebral malaria, sepsis and cytomegalovirus." (PMID 39355242, 2024). "Moreover, we found that IL10 inhibition more profoundly affected the severity of iNKT-mediated sepsis." (PMID 39355237, 2024). "Interestingly, in a sepsis model it has been shown that infants have a diminished response to IL-10 and the expression of the IL-10 receptor is strongly reduced in neonatal T-cells." (PMID 38448513, 2024). "Our results revealed a potentially protective effect of higher IL-10 levels against sepsis." (PMID 38504987, 2024). "Furthermore, the TNF-α/IL-10 ratio decreased in both groups (CLP+LF and CLP+LF-ERTA), suggesting a potential reduction in the inflammatory process associated with sepsis." (PMID 39199173, 2024). "Anti-inflammatory cytokines, IL-4 and IL-10, play crucial roles in maintaining the balance of the inflammatory response and preventing tissue damage and organ failure due to excessive inflammation during sepsis." (PMID 39502702, 2024).
Sepsis (continued). "Additionally, the levels of pro-inflammatory cytokines, such as IL-17A, IL-6, and TNF-α, were notably elevated in the Sepsis+shPIMI group, whereas the anti-inflammatory cytokine IL-10 was reduced." (PMID 39108261, 2024). "Since it has been reported that B cell-derived IL10 is critical in resolving LPS-induced acute lung injury, we next investigated whether Breg cells induced by α-GalCer can protect against sepsis." (PMID 39355237, 2024). "Higher IL-10 levels were also found in HFD fed mice compared to lean mice in a sepsis model." (PMID 39019114, 2024). "Similarly, pretreatment with GdCl3 protected against lung injury following endotoxemia and sepsis by blocking the uncontrolled release of pro-inflammatory mediators and caspase-3 and elevating IL-10 concentrations released from Kupffer cells." (PMID 38254684, 2024). "It has been reported that IL10 levels are elevated in the blood of patients with sepsis." (PMID 39355237, 2024). "Indeed, pharmacologically inhibiting EZH2 restored IL-10 secretion in vitro and increased survival in murine sepsis." (PMID 38649480, 2024). "Furthermore, when IL-10 was combined with the NEWS score, the predictive ability for identifying the risk of infection patients progressing to sepsis was significantly improved, as evidenced by comparisons of the AUC, NRI, and IDI." (PMID 39212218, 2024). "However, interestingly, prophylactic effects of α-GalCer on sepsis were significantly suppressed by treatment with an IL10 antagonist, suggesting induction of IL10-dependent anti-inflammatory responses." (PMID 39355237, 2024). "IL-10 is a crucial marker for identifying patients with worsening surgical sepsis." (PMID 39507174, 2024). "Moreover, pre-treatment with luteolin in CLP-induced sepsis mice models also showed increased Treg frequency and, thus, IL-10 production and diminished caspase-11-dependent pyroptosis in alleviating sepsis-induced lung injury." (PMID 39126050, 2024). "Similar results could be found in corresponding AUROC analysis, with IL-10 having the optimal precision and NEWS having the greatest diagnostic odds ratio for progression of infection to sepsis." (PMID 39212218, 2024). "Study found that cytokines such as CCL2/MCP‐1, IL‐10, IL‐2, and TNF‐alpha were associated with lymphocyte morphology changes and other laboratory test results related to inflammation in sepsis, and those parameters were decreased in sepsis recovery." (PMID 39305165, 2024). "DEL-1 expression is under the control of IL-10 and is essential to promote emergency granulopoiesis in neonatal sepsis, thereby facilitating sustained output of circulating neutrophils, control of bacteremia and survival from sepsis." (PMID 38263289, 2024). "To elucidate the mechanism by which α-GalCer pretreatment protects against sepsis, we considered our finding that α-GalCer pretreatment augments the iNKT10 cell subset, as prior studies have demonstrated protective effects of the anti-inflammatory cytokine IL10 in sepsis." (PMID 39355237, 2024). "Furthermore, in the late stage of sepsis, the anti-inflammatory reaction is dominant, and the increase of IL-10 level can predict the mortality of severe sepsis." (PMID 38165570, 2024). "Additionally, IL-10 administration has been shown to promote survival in a neonatal mouse model of sepsis or neonatal group B streptococcal infection." (PMID 38263289, 2024). "Notably, deficiency of IL-10 was shown to significantly worsen CpG-induced CSS to a lethal phenotype and lead the onset of an irreversible septic shock in a mouse model of sepsis induced by cecal ligation and puncture." (PMID 39530102, 2024). "IL-10 is an anti-inflammatory cytokine that plays a crucial role in the development of sepsis." (PMID 39212218, 2024). "Notably, increasing S100A9 protein phosphorylation in late sepsis MDSCs via Hotairm1 knockdown decreases the production of the immunosuppressive cytokine IL-10." (PMID 39665047, 2023).
Sepsis (continued). "However, the use of non-selective sympatholytic drugs including clonidine and dexmedetomidine attenuated the increase in plasma IL-6 and enhanced the increase in IL-10 levels in ovine sepsis, likely due to activation of anti-inflammatory cholinergic pathways." (PMID 37535121, 2023). "The analysis of the data revealed that, as compared to the sham group, the sepsis and vehicle groups had significantly (p<0.05) greater blood levels of IL-10, while serum IL-10 levels in the C21 pretreatment groups were significantly (p<0.05) greater than those in the sepsis group." (PMID 36937479, 2023). "The JAK/STAT signalling pathway involving IL10 is an important therapeutic target in sepsis." (PMID 37060578, 2023). "In addition, an exogenous supply of IL-10 promotes recovery from LPS-induced ALI, and IL-10-secreting B cells are present in sepsis-related ARDS." (PMID 37443161, 2023). "Furthermore, it has been demonstrated that septic mice survivors present high levels of IL-10 in the serum, which correlates with the coexistence of the compensatory state in sepsis survivors." (PMID 37153798, 2023). "The mechanistic basis for this paradoxical association is not fully known, however, it has been proposed that high levels of IL-10 may prevent the clearance of nosocomial infections leading to sepsis." (PMID 38094302, 2023). "Thus, the concomitant reduction of circulating neutrophils in combination with increased plasma IL-10 levels and increased circulating Ly6Chigh monocytes suggest that mice exhibit an anti-inflammatory state 7 days after the onset of sepsis." (PMID 36911737, 2023). "In a cecal ligation and puncture-induced sepsis model macrophages isolated from HBO2-treated mice demonstrated enhanced IL-10 secretion as compared with controls, and IL-10 deficiency mice were not protected from sepsis mortality by IL-10 expression." (PMID 37627293, 2023). "We have previously shown that IL-10 production is associated with MDSC accumulation in mice during late sepsis and that mice lacking the S100a9 gene do not generate immunosuppressive MDSCs and have significantly less IL-10." (PMID 39665047, 2023). "PDCD4 promotes sepsis through activation of the NF-κB pathway and inhibition of IL-10 production." (PMID 38132140, 2023). "By inducing the expansion of IL-10 secreting M2 macrophages, and promoting the accumulation of regulatory T cells (Tregs), IL-33 has been proposed as a potential mediator of long-term immunosuppression in murine models of sepsis." (PMID 37662933, 2023). "Future studies including a group of polytrauma patients with sepsis should analyse whether the development of sepsis is reflected in exosomal cytokines, and if exosomal IL-10, which was found to be constant in our study, increases in these patients." (PMID 37511589, 2023). "In patients who developed sepsis after trauma, a reduced amount of systemic IL-10 was measured." (PMID 37511589, 2023). "Furthermore, using anti-inflammatory cytokines, such as IL-10, to treat sepsis is also worth considering." (PMID 36776839, 2023). "Late sepsis Gr1+CD11b+ cells produce increased amounts of the immunosuppressive IL-10 cytokine." (PMID 39665047, 2023). "Having said that, a comparison of the safety and therapeutic effect of wild-type hASCs and human mesenchymal stem cells (hMSCs) transiently expressing CXCR4 and IL-10 was made, aiming to generate an improved anti-inflammatory response for sepsis, in addition to standard antibiotic treatment." (PMID 38203690, 2023). "Granulocytes, in particular neutrophils, were shown to produce IL-10 during sepsis in mice." (PMID 37936714, 2023). "Based on our data showing an increase in IL-10 concomitant with restrained proinflammatory cytokine levels in immunized mice, we hypothesized that IL-10 production would be a requirement for MDSC-mediated protection against sepsis." (PMID 37681975, 2023). "In the early phase of sepsis, IL-10 provides a protective effect." (PMID 37626822, 2023).